RNU6-325P (RNA, U6 small nuclear 325, pseudogene)
Gene: Small nuclear RNA gene on chromosome 10 (85,537,379 to 85,537,483, forward strand). Ensembl gene ENSG00000223064.
Homologues: Orthologues: chimpanzee U6 (98% identical), macaque U6 (92% identical), dog U6 (76% identical), guinea pig U6 (63% identical), mouse Gm23858 (62% identical). Paralogues in human: RNU6-1131P (81% identical), RNU6-166P (80% identical), RNU6-1175P (79% identical), RNU6-11P (79% identical), RNU6-242P (79% identical), RNU6-354P (79% identical), RNU6-37P (79% identical), RNU6-41P (79% identical), RNU6-45P (79% identical), RNU6-610P (79% identical), RNU6-838P (79% identical), RNU6-10P (78% identical), and 1281 more.